GPX4 (glutathione peroxidase 4)
Diseases named in the same sentence as GPX4 in open-access papers (continued):
Sharing a sentence is not in itself a finding about the gene and the disease.
non-small cell lung carcinoma (continued). "Similarly, gefitinib resistance is linked to enhanced ferroptosis defense mechanisms, and inhibiting discoidin domain receptor tyrosine kinase 1 and GPX4 can restore ferroptosis and overcome gefitinib resistance in non-small cell lung cancer and triple-negative breast cancer, respectively." (PMID 39935430, 2025). "For example, in non-small cell lung cancer (NSCLC), METTL3 acts as a catalyst for ferroptosis by targeting GPX4 and SLC7A11." (PMID 40271153, 2025). "In non-small cell lung cancer, hypoxia-inducible factor (HIF)-1α inhibits ferroptosis by activating the Hippo–YAP signaling pathway, and YAP1 upregulates GPX4 expression." (PMID 37773303, 2024). "For instance, lncRNA NEAT1 regulates ferroptosis sensitivity in non-small-cell lung cancer by interacting with ACSL4 and GPX4." (PMID 39280701, 2024). "The Tim-AIII-HSP90 complex triggers ferroptosis in non-small cell lung cancer (NSCLC) through targeting ubiquitination and degradation of GPX4." (PMID 38738174, 2024). "The combination of ginkgetin and cisplatin (DDP) decreased the SLC7A11 and GPX4 expression as well as the GSH/GSSG ratio and increased labile iron pool and lipid peroxidation to mediate ferroptosis in EGFR wild-type non-small-cell lung cancer." (PMID 39021832, 2024). "In non-small cell lung cancer, NRF2 upregulates GPX4 and superoxide dismutase 2, conferring resistance to epidermal growth factor receptor tyrosine kinase inhibitors, which can be overcome by inhibiting GPX4 to induce ferroptosis." (PMID 39935430, 2025). "A GPX4-targeted photosensitizer, by integrating ML210 with photodynamic therapy, reverses the hypoxic tumor microenvironment’s inhibition of ferroptosis for non-small-cell lung cancer therapy." (PMID 40427071, 2025). "On the other hand, NEAT1 inhibits erastin-induced ferroptosis by not only increasing GPX4 and SLC7A11-mediated antioxidative pathways but also decreasing ACSL4-mediated lipid peroxidation, which may confer the resistance to erastin in non-small cell lung cancer (NSCLC) cells." (PMID 35625948, 2022). "For example, class I FINs targeting SLC7A11, such as erastin and sulfasalazine (SAS), class II FINs targeting GPX4, such as RSL3 and ML162, and class III FINs depleting CoQ and GPX4, such as FIN56, could all sensitize non-small cell lung cancer cells to RT in vitro." (PMID 33891303, 2021).
Cognitive impairment (41 papers, 2020 to 2026). Abnormal cognition is characterized by deficits in thinking, reasoning, or remembering. "Selenium (Se), a crucial regulator of GPX4 function and essential for brain health, is associated with cognitive impairment and AD pathology." (PMID 40475985, 2025). "GPX4 knockout mice were shown to have significant hippocampal neuronal loss and cognitive impairment." (PMID 36385946, 2022). "GPX4 is a key regulator of ferroptosis, and experimental studies have shown that mice with GPX4 ablation of forebrain neurons have cognitive impairment and neuronal damage and loss at the hippocampal level." (PMID 35844784, 2022). "GPX4-deficient mice exhibit hippocampal neurodegeneration and cognitive impairment." (PMID 39635435, 2024). "Research has shown that the deletion of SLC7A11 or GPX4 in mice could cause ferroptosis-like damage, lead to cognitive impairment and neurodegeneration, and even show early embryonic lethality." (PMID 36909944, 2023). "Loss of GPX4 is a crucial event in ferroptosis, and promotes cognitive impairment." (PMID 36978979, 2023). "Together, these findings consolidate the rationale for targeting GPX4 in cognitive impairment post-TBI therapy." (PMID 41369366, 2025). "The results showed that mTBI rats exhibited cognitive impairments, increased lipid peroxidation, and reduced GPX4 expression." (PMID 41261172, 2025). "In conclusion, MSC - Exos alleviate cognitive deficits after mTBI by inhibiting ferroptosis via PI3K/AKT/mTOR - mediated upregulation of GPX4, providing a novel therapeutic strategy for mTBI." (PMID 41261172, 2025). "For example, median nerve stimulation (MNS) has been shown to upregulate GPX4, alleviate oxidative stress, inhibit ferroptosis, and ameliorate cognitive deficits in TBI rats." (PMID 41369366, 2025). "GAS has been shown to enhance the antioxidant capacity and inhibit ferroptosis through the Nrf2/Keap1-glutathione peroxidase 4 (GPx4) pathway, thus improving cognitive impairment in rats with VD." (PMID 39776583, 2024). "Some studies have shown that ferroptosis is associated with hippocampal neuron damage, and DFO can activate the nuclear factor erythroid 2-related factor 2/GPX4 signaling pathway, thereby alleviating hippocampal injury and cognitive impairment in SAE mice." (PMID 38685023, 2024). "Activation of PI3K/AKT/Nrf2 was shown to improve cognitive impairment after cerebral ischemia by up-regulating GPX4 to inhibit ferroptosis." (PMID 38738174, 2024). "One of our previous studies found that low‐dose APAP reduced cognitive impairment and enhanced survival in septic mice; therefore, we first examined the GPX4 pathway mechanism in vitro." (PMID 37443407, 2023). "In mice models, deletion of GPX4 led to AD-like degeneration in the hippocampus and cognitive decline, whereas overexpression of GPX4 in 5xFAD mice AD model did ameliorate cognitive impairment and neurodegeneration." (PMID 35625641, 2022). "The role of GPX4 in ferroptosis is particularly important, studies reported that deletion of GPX4 in forebrain neurons promotes cognitive impairment and neurodegeneration." (PMID 34335271, 2021). "Ablation of Gpx4 in forebrain, the frequently affected region in AD pathology, leads to cognitive impairment and hippocampal neurodegeneration in Gpx4 brain inducible knockout (Gpx4BIKO) mice." (PMID 34422824, 2021). "Given that the key role of GPX4 for the maintenance of neuronal function, selective deletion of GPX4 in the brain contributes to cognitive impairment and neurodegeneration." (PMID 33362556, 2020). "Our study suggests that EA may improve cognitive impairment in aged mice with PND by inhibiting ferroptosis in hippocampal neurons through the SIRT1/NRF2/GPX4 pathway." (PMID 41527519, 2026). "Furthermore, methyltransferase-like 3 (METTL3) elevated GPX4 levels by enhancing its mRNA stability, thereby suppressing ferroptosis and ameliorating cognitive impairment post-TBI." (PMID 41369366, 2025).
Cognitive impairment (continued). "Furthermore, intermittent fasting has been shown to upregulate GPX4 expression, inhibit ferroptosis, and ameliorate cognitive deficits post-TBI, suggesting another promising therapeutic strategy for similar applications." (PMID 41369366, 2025). "MSC-Exos restore GPX4 expression, suppress ferroptosis, and mitigate cognitive impairment." (PMID 41261172, 2025). "Also, a study has demonstrated that moderate-intensity treadmill exercise downregulates TfR expression and upregulates GPX4, rescues ferroptosis, and thereby attenuates cognitive impairment post-TBI." (PMID 41369366, 2025). "The activation of the Nrf2/GPX4 signaling pathway by deferoxamine preconditioning could significantly reduce the levels of ferroptosis in hippocampal neurons and improve cognitive impairment." (PMID 35190654, 2022). "In addition, ferroptosis modulated sevoflurane-induced cognitive impairment through interaction between Mind bomb-2 (Mib2) and glutathione peroxidase 4 (Gpx4)." (PMID 36238640, 2022). "In brain, ferroptosis induced by depletion of neuronal glutathione peroxidease 4 (GPX4), could lead to cognitive impairment, while ferroptosis inhibition alleviates cognitive disorder." (PMID 36386192, 2022). "Also, GPX4 downregulation has been reported in different cognitive impairment mouse models." (PMID 39941034, 2025). "The ablation of GPX4 and glutathione depletion (GSH) worsen cognitive impairment and neurodegeneration in animal models, supporting the connection between ferroptosis and AD pathogenesis." (PMID 40475985, 2025). "Anacardic acid (AA) and Fer-1 exert comparable neuroprotective effects against cognitive impairment post-TBI by mitigating ferroptosis through a concerted mechanism involving TfR downregulation and GPX4 upregulation." (PMID 41369366, 2025). "RY-A inhibited oxidative stress and ferroptosis by activating the System Xc-/GSH/GPX4 pathway and balancing iron metabolism, thereby attenuating CCH-induced neurological damage and cognitive deficits." (PMID 40070574, 2025). "The results demonstrated that during HIBI, ferroptosis occurs via the SIRT1/Nrf2/GPx4 signaling pathway, suggesting it as a potential therapeutic target for inhibiting ferroptosis and ameliorating HIBI‐induced cognitive impairments." (PMID 36184790, 2022). "Additionally, acetaminophen has been found to prevent ferroptosis in hippocampal tissues of septic mice through activation of the GPX4/FSP1 pathway, thereby reducing hippocampal damage and alleviating cognitive deficits while improving survival rates in septic models." (PMID 40551190, 2025).
Stroke (40 papers, 2014 to 2026). Sudden impairment of blood flow to a part of the brain due to occlusion or rupture of an artery to the brain. "GSH levels and GPX4 levels have been strongly associated with stroke." (PMID 37622048, 2023). "The c.660T > A (rs713041) polymorphism of the GPX4 gene and stroke risk." (PMID 33808851, 2021). "Our results also show that the c.660T > A (rs713041) of the GPX4 gene may be associated with stroke occurrence." (PMID 33808851, 2021). "Novel CSF and plasma biomarkers such as oxylipins (oxidized lipid mediators), GPX4 fragments, and 8‐iso‐prostaglandin F2α have been identified as indicators of ferroptosis activity and oxidative lipid damage in stroke patients." (PMID 41540791, 2026). "Overall, stroke‐induced neuronal ferroptosis was suppressed by inhibiting the downregulation of GPX4." (PMID 40873639, 2025). "From 6 h to 14 days after stroke, acupuncture significantly increased brain tissue GPX4 levels at various time points: GPX4‐6h: I2 = 0%, SMD: 2.71, 95% CI [1.31, 4.12], p < 0.0001." (PMID 40842100, 2025). "Experimental models show that GPX4 overexpression alleviates cerebral injury after stroke, whereas GPX4 deletion exacerbates infarction." (PMID 41425599, 2025). "A growing body of research suggests that stroke often have functional inhibition of systems XC- and GPX4, decreased GSH, and increased oxidative stress." (PMID 39420985, 2024). "Inhibition of ferroptosis and promotion of the levels of glutathione peroxidase 4 (GPX4) by selenium significantly protect neurons after stroke." (PMID 36819784, 2023). "Depletion of GPX4 was observed during stroke‐induced ferroptosis, and up‐regulation of GPX4 expression can protect neural functions from ferroptosis injuries." (PMID 37480159, 2023). "This high percentage of homology between mouse, rat, and human TfR1 and GPX4 promoter sequences indicates the relevance of our results obtained in animal models of stroke to human brain ischemia." (PMID 37324938, 2023). "Regarding stroke, selenium supplementation directly into the brain induced the expression of antioxidant glutathione peroxidase 4, which further inhibited the ferroptosis of neurons in a brain hemorrhage model." (PMID 35495125, 2022). "The expression of GPX4 is closely related to ferroptosis after stroke as it is able to inhibit lipid peroxidation." (PMID 34149358, 2021). "Attempts to boost GPx4 directly or indirectly in animal models of neurodegenerative diseases and stroke have been successful, but remained unfeasible and inefficient in clinics." (PMID 33568697, 2021). "At day 14 after stroke, a trend of enhanced expression of rat reelin and GPx-4 mRNA was detected in sham and cbMNC-treated animals compared with the PBS group." (PMID 24690461, 2014). "Inhibiting the downregulation of GPX4 can suppress stroke‐induced neuronal ferroptosis." (PMID 40873639, 2025). "Chronic or repeated interventions—such as regular EA at acupoints like DU20 and ST36 of stroke models—have been shown to persistently upregulate protective enzymes, including GPX4, while maintaining balanced expression of key iron transporters like TfR1 and FTH1." (PMID 40365351, 2025). "Conversely, GPX4 activators, including selenium compounds like selenomethionine and selenocysteine‐containing peptides like Tat SelPep, have demonstrated the ability to alleviate DOX‐induced cardiomyopathy and promote stroke recovery by suppressing GPX4‐dependent ferroptosis." (PMID 39568772, 2024). "Studies have shown that stroke may lead to decreased GSH synthesis through inhibition of glutathione peroxidase 4 (GPX4)." (PMID 38992073, 2024). "We investigated the possible interaction between HDAC9 and transcriptional factors involved in stroke pathophysiology, that are able to activate in a sequence specific manner their target genes TfR1 22 and GPX4 26, such as HIF-1 and Sp1 in SH-SY5Y cells after OGD/Rx." (PMID 37324938, 2023).
Stroke (continued). "Therefore, we observed the effects of kaempferol on protein levels of SLC7A11, GPX4, and Nrf2 in an in vitro stroke model of OGD/R." (PMID 34206421, 2021). "Both GSH depletion and GPx4 deficiency are highly relevant conditions, as GPx4 catalyzes the reduction of lipid peroxides at the expense of GSH, and as levels of both GSH and GPx4 are reduced in stroke and neurodegenerative diseases." (PMID 33568697, 2021). "We hypothesize that single nucleotide polymorphisms (SNPs) in the SOD2, CAT, GPX4, NOS1 and NOS2 genes might be associated with altered susceptibility to oxidative stress and stroke development." (PMID 33808851, 2021). "Furthermore, silencing of HDAC9 also prevented HIF-1 increase, Sp1 decrease, and consequently, the modulation of their target genes TfR1 and GPX4 in neurons in in vitro and in vivo models of stroke as demonstrated by Western blot and immunohistochemistry experiments." (PMID 37324938, 2023). "This modulation is specifically characterized by the upregulation of GPX4 and downregulation of ACSL4 within ischemic penumbra tissues in mice post‐stroke." (PMID 40376919, 2025). "Acupuncture can reduce lipid peroxidation by upregulating the expression of antioxidant enzymes such as GPX4, SOD, and CAT in the brain tissue of MCAO/R rat models following stroke." (PMID 40365351, 2025). "In this study, four biomarkers, CDKN1A, GPX4, PRDX1, and PRDX6, were used to diagnose stroke and assess the treatment effects." (PMID 38360841, 2024). "Following a stroke, the levels of GSH and GPX4 expression decrease, impeding the prompt elimination of the oxidative stress reaction and worsening ferroptosis." (PMID 37622048, 2023). "The reserve of GSH is consumed by constant Fenton reaction induced by mass labile iron during stroke and neurodegenerative diseases, leading to a decline in the concentration of GSH as enzymatic reactants, which in turn inhibits GPX4 activity." (PMID 37377861, 2023). "In recent years, much emphasis has been placed on understanding the direct effects of GPX4 and GSH on stroke." (PMID 36425577, 2022). "Our data showed that the ferroptosis biomarker GPx4 and COX2 both changed correspondingly after stroke." (PMID 33889074, 2021). "We used liproxstatin-1 to inhibit ferroptosis and found that changes in GPx4 and COX2 were inhibited after stroke, which further explained the occurrence of ferroptosis after stroke." (PMID 33889074, 2021). "In conclusion, our results showed that the genetics variants in the SOD2 (c.47T > C; rs4880), GPX4 (c.660T > A; rs713041), NOS1 (g.117803515C > T; rs1879417) and NOS2 (c.1823C > T; rs2297518 and c.-227G > C; rs10459953) genes may be associated with individual susceptibility to a stroke." (PMID 33808851, 2021). "XMZS may activate NRF2/GPX4/SLC7A11 pathway to treat stroke by attenuating neuronal ferroptosis and is applicable in clinical management of stroke." (PMID 41822239, 2026). "Our findings suggest that acupuncture may regulate ferroptosis, mitigate stroke‐induced neuronal damage, and enhance neurological recovery in stroke animal models by modulating key antioxidants such as GSH, GPX4, and SOD." (PMID 40842100, 2025). "The data revealed that MGF significantly upregulated the expression of NRF2, GPX4, SLC7A11 and FTL, whereas ML385 inhibited the influence of MGF on these proteins, suggesting that MGF might inhibits ferroptosis in stroke by targeting the NRF2/ARE pathway." (PMID 40474971, 2025). "Collectively, the results of the present study suggest that stroke induced an increase in HDAC9 in the cytosol of neurons activating the pro-ferroptotic pathway HIF-1/TfR1 and reduces the anti-ferroptotic pathway Sp1/GPX4." (PMID 37324938, 2023). "However, current research is focused primarily on the effects of GPX4 and GSH on stroke, and a large gap persists in our understanding of the upstream regulatory mechanisms; this therefore requires further investigation." (PMID 35481263, 2022).
Stroke (continued). "It has been established that the levels of intracellular lipid peroxides and Fe2+ are increased during stroke, and ferroptosis inhibitors can upregulate the levels of GSH, GPX4 or system Xc− to alleviate brain damage, indicating that ferroptosis affects the progression of stroke." (PMID 36425577, 2022). "The baicalin, carthamin yellow, dauricine, (−)-epicatechin, kaempferol, and paeonol ameliorate neuronal ferroptosis in vitro or in vivo stroke models via regulating ACSL4, GPX4, TFR1, Fe2+, and NRF2 pathways, which show great potential in the treatment of stroke." (PMID 35264947, 2021). "Furthermore, since HDAC1 and 2, belonging to class I HDACs, and HDAC4 and 5, belonging to class II HDACs, increase in an in vitro model of stroke 30, 39, we investigate the specificity of HDAC9, among HDACs isoforms, in the modulation of TfR1 and GPX4 after ODG/Rx." (PMID 37324938, 2023). "Moreover, evidence shows that promoting GPX4 activity and supplementation of GSH in neurodegenerative diseases and stroke both can mitigate oxidative stress and inflammatory pathology related to ferroptosis, thereby contributing to better preservation of executive functioning longitudinally." (PMID 37377861, 2023).